RNU6-722P (RNA, U6 small nuclear 722, pseudogene)
Gene: Small nuclear RNA gene on chromosome X (48,959,179 to 48,959,282, reverse strand). Ensembl gene ENSG00000223309.
Homologues: Orthologues: chimpanzee U6 (99% identical), macaque U6 (99% identical), rat LOC120095351 (83% identical), mouse Gm24086 (74% identical), guinea pig U6 (63% identical). Paralogues in human: RNU6-11P (88% identical), RNU6-37P (88% identical), RNU6-43P (88% identical), RNU6-1 (87% identical), RNU6-15P (87% identical), RNU6-2 (87% identical), RNU6-33P (87% identical), RNU6-3P (87% identical), RNU6-4P (87% identical), RNU6-5P (87% identical), RNU6-6P (87% identical), RNU6-7 (87% identical), and 1291 more.